GCNT7 (glucosaminyl (N-acetyl) transferase family member 7)
Description:
Probable glycosyltransferase.
Synonyms: C20orf105; dJ1153D9.2; gcnt
Tractability: Antibody: UniProt predicts a signal peptide or a membrane-spanning region.
Gene: Protein-coding gene on chromosome 20 (56,491,492 to 56,525,925, reverse strand). Ensembl gene ENSG00000124091.
Subcellular location: Golgi apparatus membrane
Subcellular location (Human Protein Atlas): Nuclear bodies; Vesicles; Cytosol
Pathways (Reactome):
Metabolism of proteins: O-linked glycosylation of mucins
Gene Ontology:
Molecular function: acetylglucosaminyltransferase activity; glycosyltransferase activity; UDP-glycosyltransferase activity
Cellular component: Golgi membrane; membrane
Genetic constraint (gnomAD): Loss-of-function variants: 25 observed, 28.73 expected, observed/expected ratio (o/e) 0.87, 90% interval 0.63 to 1.22. The upper end of that interval is the gene's LOEUF score, 1.22, which puts it in group 5 of 6, group 1 being the genes least tolerant of losing a copy. Missense variants: 351 observed, 387.25 expected, observed/expected ratio (o/e) 0.91, 90% interval 0.83 to 0.99. Synonymous variants: 128 observed, 136.83 expected, observed/expected ratio (o/e) 0.94, 90% interval 0.81 to 1.08.
Homologues: Orthologues: macaque GCNT7 (87% identical), pig GCNT7 (80% identical), dog GCNT7 (78% identical), rabbit GCNT7 (76% identical), guinea pig GCNT7 (71% identical), rat Gcnt7 (65% identical), mouse Gcnt7 (65% identical), tropical clawed frog gcnt7 (59% identical), zebrafish gcnt7 (54% identical), Caenorhabditis elegans gly-16 (22% identical), Caenorhabditis elegans gly-18 (21% identical), Caenorhabditis elegans gly-19 (21% identical), and 16 more. Paralogues in human: GCNT2 (51% identical), GCNT4 (37% identical), GCNT3 (36% identical), GCNT1 (34% identical), XYLT2 (22% identical), XYLT1 (21% identical), WSCD1 (13% identical), WSCD2 (11% identical).
Diseases named in the same sentence as GCNT7 in open-access papers:
GCNT7 is named in the same sentence as 1 disease in open-access papers, as found by Europe PMC text mining. Sharing a sentence is not in itself a finding about the gene and the disease. The quoted sentences say what the papers report.
diarrheal disease (1 paper, 2022). The condition of having at least three loose or liquid bowel movements each day. "Our study reports five such proteins, RAPH1, GCNT7, ADAMTS1, GLI1, and SEC31B, which are strong binding partners of other significant proteins and could thus be targeted for the discovery of a common medication system against diarrheal disease." (PMID 36473896, 2022).